CD4 (CD4 molecule)
Diseases named in the same sentence as CD4 in open-access papers (continued):
Sharing a sentence is not in itself a finding about the gene and the disease.
tumor (continued). "In consideration of the MBD2 expression were highly correlated to immune cells quantity, especially for activated CD4+ and CD8+ T-cells, as well as its preferable prognostic value, we next thoroughly analyzed the role of MBD2 in tumor immune environment formation." (PMID 36276973, 2022). "In the syngeneic B16 melanoma cell line transfer system, B cell depletion by anti-CD20 antibody treatment resulted in a two-fold bigger tumor volume and impaired interferon-γ (IFN- γ) and tumor necrosis factor (TNF-α) production from CD4+ T cells and CD8+ T cells." (PMID 36033455, 2022). "Thus, we evaluated CD4+ and CD8+ T cells expression in the tumor tissue following immunofluorescence staining." (PMID 37693071, 2022). "This tumor rejection was immune-mediated, as athymic nude mice and mice depleted of T CD4+, or T CD8+ cells lacked protection." (PMID 36144933, 2022). "Tumour cells induce DCs to secrete TGF‐β and stimulate FOXP3+/CD4+/CD25+ Tregs proliferation." (PMID 36305631, 2022). "Multiple studies have shown that these ingredients could enhance the expression of CD8+T cells and NK cells, promote the infiltration of CD4+T cells and CD8+T cells and inhibit inflammation to enhance the anti-tumor effect of the body 39-41." (PMID 36118529, 2022). "CD4+ T cells are necessary for the priming and differentiation of CD8+ T cells and support durable tumor-specific cytotoxic T cell responses by instructing the downregulation of coinhibitory receptors and enhancing the capacity of CD8+ T cells to infiltrate tumors." (PMID 36385379, 2022). "We found that FAM207A interacts with CD4+ memory T cells and ST3GAL4, and their activation was negatively correlated with FAM207A expression (R = –0.28), indicating that FAM207A is a potential tumor biomolecular target." (PMID 35102149, 2022). "Combination treatment also increased intra-tumoral CD8+ T cells (but not CD4+ cells) and decreased both tumor-infiltrating myeloid cells and monocytic MDSCs." (PMID 34753889, 2022). "Furthermore, we found that the numbers of CD3+, CD4+ and CD8+ T cells in tumor samples were generally higher than those in normal tissue in PTC-WO, but the numbers of CD3+, CD4+ and CD8+ T cells were similar between tumor and normal tissue in PTC-W." (PMID 35720279, 2022). "Furthermore, heterogeneity and levels of target expression constitute an important issue and contacts of malignant and T cells are contingent on the baseline levels of CD4 and CD8 T-cell infiltration in the tumor microenvironment." (PMID 35154495, 2022). "Furthermore, using additional immune deconvolution tools, we also demonstrated that several immune cells which primarily responsible for effective anti-tumor immunity, such as CD8+ T cell, CD4+ T cell and B-cells, were infiltrated higher in the low-risk group." (PMID 36389757, 2022). "Of the 63 tumor tissues, 31 (49.2%) of them were positive for intratumoral lymphocyte (CD4+ and CD8+) infiltration, and 15 (23.8%) were positive for stromal lymphocyte (CD4+ and CD8+) infiltration." (PMID 36568391, 2022). "The change in the ratio of CD4+T-cell, CD8+T-cell, may be attributed to the migration of immune cells populations to the developed tumor, leading to a significant reduction of the same population in the spleen." (PMID 35999584, 2022). "Conversely, a strong positive correlation (r = 0.783, p < 0.0001) was observed between levels of FoxP3+ Tregs and CD4+TIM-3+ T cells in tumor tissues but not in normal tissues." (PMID 35455287, 2022). "This study indicated that P2RX1 is significantly positively correlated with tumor-infiltrating immune cells and their biomarkers in BC, including B cell, CD8+ T cell, CD4+ T cell, macrophage, neutrophil, and dendritic cell, revealing the important role of P2RX1 in BC immune modulation." (PMID 35585027, 2022). "Targeting the TME to increase CD4+ and CD8+ T-cell counts and the CD8+/FOXP3+ cell ratio could decrease tumor recurrence and improve clinical outcomes." (PMID 36225934, 2022).
tumor (continued). "Moreover, PDA CD73 was shown to correlate with a decrease in CD4+, CD8+ and CD21+ tumor-infiltrating lymphocytes suggesting it plays an important role in immunosuppression and tumor progression." (PMID 36147911, 2022). "CD4+ and CD8+ T cells can further enhance the anti-tumor immune response by secreting cytokines." (PMID 35945754, 2022). "There was a significant correlation between DES gene expression and tumor purity, B cell infiltration, CD8+T cell infiltration, CD4+T cell infiltration, macrophage infiltration, and dendritic cell infiltration, and the differences were all statistical significance." (PMID 35174205, 2022). "Since IL-17 also acts as tumor suppressor during the process of tumorigenesis by enhancing NK cell and CTL cell activation, and recruiting neutrophil, NK cell, CD4 + and CD8 + T cell infiltration into tumor tissues, its reduced levels would favor the development of cancer lesions." (PMID 35804458, 2022). "Several studies have shown the involvement of CD4+ helper T cells in tumor immunity and response to ICB, which is distinct from their prominent role in inducing tumor-reactive cytotoxic T cells." (PMID 35236758, 2022). "Most available studies investigated expression of ICs in bulk tumor tissues but not on specific CD4+ and CD8+ T cell subsets." (PMID 35655158, 2022). "PD-1 expression in CD4+T cells was reduced in spleens, but not tumours and draining lymph nodes of carcinogen-induced Stat1−/− mice compared to Stat1+/+ mice." (PMID 35595823, 2022). "Among the CD4 T cells infiltrating HNSCC, 30–40% of the cells are Treg cells, involved in regulating immune responses, preventing immune pathologies, and thus limit anti-tumor immune responses." (PMID 35937775, 2022). "Similarly, it has been reported that the abundance of infiltration of CD4+ T and CD8+ T cells plays an important role in immunotherapy by enhancing the immune response to tumor cells." (PMID 35812755, 2022). "The lack of CD8+ and CD4+ T cells each leads to noticeable increases in tumor incidence, implicating the importance of T cells in surveillance and subsequent tumor eradication." (PMID 35434271, 2022). "Low CD4+ levels did not resolve after the treatment of the tumor itself, remaining below control values even after a 36-month follow-up." (PMID 35804830, 2022). "Strikingly, although tumor cell kill was comparable between the T-cell subsets, at least twofold differences in GZMB production were observed when comparing CD4+ memory and CD8+ naive T cells to CD4+ naive and CD8+ memory T cells." (PMID 36271507, 2022). "Indeed, immunization with ASPH-loaded dendritic cells or ASPH-expressing λ phage constructs suppressed tumor cell growth in a mouse model of HCC; both CD4+ and CD8+ effector T(eff) cells contributed to tumor suppression." (PMID 36293298, 2022). "CD3+ T cells, CD4+ T cells, and CD8+ T cells were lower in tumor samples than para-tumor samples." (PMID 35530333, 2022). "DNAJB1-PRKACA-derived HLA class I and HLA class II ligands induce multifunctional cytotoxic CD8+ and T-helper 1 CD4+ T cells, and their cellular processing and presentation in DNAJB1-PRKACA expressing tumor cells is demonstrated by mass spectrometry-based immunopeptidome analysis." (PMID 36302754, 2022). "Additionally, the tumor immunity response to both treatments was quite different, as implied from the elevated expression levels of immune cell markers, including CD8, CD4, CD3 and CD45, as well as antitumor effector cytokines including IFN-γ and TNF-α." (PMID 35154474, 2022). "Furthermore, PBLs from patients with MPC showed a greater proportion of CD4+CD25+FOXP3+ Tregs, exhausted CD8+CTLA4+ T cells, CD8+CD122+ T cells, and CD8+CD45R+ T cells, which can be regarded as tumor-promoting cells, than in patients with BPC." (PMID 36333670, 2022).
tumor (continued). "In the tumour site, abundant ROS induced degradation of the hydrogel that locally released gemcitabine (GEM) and anti-PD-L1 blocking antibodies (aPDL-1), triggering marked infiltration of CD4+ and CD8+ T lymphocytes and even systemic immune responses that inhibited tumour growth and recurrence." (PMID 35668923, 2022). "NK cells were critical for the anti-tumor activity of this combination but not T lymphocytes, as shown by the effects exerted by the depletion of CD4+ and CD8+ T lymphocytes." (PMID 36294305, 2022). "To clarify the potential mechanisms underlying IL-8-mediated LNM, we performed profound bioinformatics analysis, and systematically assayed the CD4/CD8 ratio and PD-1 expression of T cells in primary tumor tissues, TDLNs and NDLNs, and evaluated their relevance with elevated IL-8 levels." (PMID 35633411, 2022). "Levels of B, natural killer (NK), and CD4+ cells did not change significantly during tumor progression." (PMID 35677048, 2022). "Fortunately, immunophenoscore was developed to comprehensively quantify tumor immunogenicity by integrating antigen processing (MHC), checkpoints, immunomodulators, effector cells (activated CD8, activated CD4, Tem CD4, Tem CD8, and suppressor cells (Treg and MDSC)." (PMID 36357897, 2022). "While it was gratified that the treatment of PB-Gel and PQ/PB-Gel could effectively improve the plight of fewer CD4+ and CD8+ T cells in “cold” tumor infiltration, respectively." (PMID 35832081, 2022). "Another study examining the MHC-II-negative CT26 tumor model found that following treatment with peptide immunization in the absence of Tregs, tumor-specific CD4+ T cells were able to reject the tumor." (PMID 36159781, 2022). "Regards the tumor expansion, the immune microenvironment, certain infiltrating immune cells (i.e., CD3, CD4, CD8, CD68 positive cells) were thought to play certain roles in progression-free survival (PFS) of PDAC after radical resection, yet it is need to be further verified in PDAC LTSs." (PMID 34255132, 2022). "Furthermore, the author found that there were more CD4+ and CD8+ T-cells present in the tumor tissue of these patients with early disappearance of circulating T-cells." (PMID 36776373, 2022). "Among these 28 types of immune cells, 12 types of immune cells, such as activated CD4 T cell and activated CD8 T cell, are considered to execute anti-tumor immunity; while 8 types of immune cells, such as regulatory T cell and type 2 T helper cell are considered having immune-suppressive functions." (PMID 35664300, 2022). "This may be correlated with the propagation of CD3+, CD4+, and CD8+ T3 cells, which inhibit tumor cell growth." (PMID 36146527, 2022). "In addition, we noticed that the CD44−CD62L+ naïve subsets of CD4+ and CD8+ T cells were decreased in tumor-bearing mice compared with those in naïve mice, indicating their activation under tumor growth conditions." (PMID 35173168, 2022). "Conversely, eosinophil and macrophage tumor infiltration were absent in vaccinated CD4 knockout mice." (PMID 36159781, 2022). "ssGSEA showed that the levels of tumor-infiltrating immune cells, including activated B cells, activated CD8 T cells, effector memory CD8 T cells, activated CD4 T cells, CD56+ natural killer (NK) cells, and T follicular helper cells, were significantly higher in ImmCluster A than in ImmClusterB." (PMID 36177001, 2022). "However, analysis of CT26 tumor-infiltrating immune cells demonstrated a significant decrease in regulatory T cells (CD3+; CD4+; FOXP3+) when RXC004 was combined with anti-PD-1 treatment over control or either monotherapy." (PMID 36922934, 2022). "CD4+CD69+FOXP3− Tregs accounted for the vast majority of tumor‐infiltrating Tregs compared with FOXP3+ Tregs and could suppress the CD4+ T‐cell response mainly through mTGF‐β1." (PMID 35474948, 2022).
tumor (continued). "When comparing cellular composition in LUSC and LUAD in primary tumor tissue with cancer cells as reference cell type, we found a significantly higher proportion of neutrophils in LUSC, whereas macrophages, CD4+ T cells, alveolar cells type 2, and transitional club/AT2 were more abundant in LUAD." (PMID 36368318, 2022). "CD8+ T cell depletion abolished most tumor retardation, while depletion of CD4+ T cells or NK cells did not affect tumor growth inhibition compared with the I.T. vaccine group." (PMID 35623658, 2022). "The significant upregulation of CD4 Th1 and Th2 response signatures in VISTA high expressors indicates an immune activation directed toward class II HLA-restricted tumor antigens and, therefore, a potential vulnerability of AML cells via a mechanism of immune editing." (PMID 36499220, 2022). "On the other hand, CD4+/CD8+ T cell recruitment and tumor infiltration were investigated." (PMID 35547769, 2022). "Moreover, miR-570 overexpression promoted T cell activation and proliferation, as shown by a lower ratio of CD3+ CD4+ T cells and higher ratio of CD8+ IFN-γ+ T cells in peripheral blood and tumor tissues of miR-570 mimics-treated mice." (PMID 35883486, 2022). "We compared the Ki67 expression in the proliferating epithelial tumor cells neighbored by CD8+ or CD4 + T-cells as compared to cells without these cells as neighbors." (PMID 35149709, 2022). "However, some CD4+ Th cells, such as Treg cells, can also suppress anti-tumor immune response; they strongly exert immune suppression by inducing CTL exhaustion in tumor microenvironment." (PMID 35523765, 2022). "Additionally, despite one patient having a large number of unique CD4+ and CD8+ T-cell clonotypes, the actual number of clonotypes identical to those from the relapsed tumor was significantly lower." (PMID 36011015, 2022). "Moreover, TILs positive for CD3, CD4, CD8 and PD-1 were found to be positively correlated with PD-L1 expression in the tumour, and the PD-L1 levels observed in IHC were positively correlated to quantitative reverse transcription PCR (RT-qPCR) values." (PMID 35158816, 2022). "Additionally, contrary to the tumor results of RNF125-OE, reduced expression of CD4, CD8, and F4/80 in RNF125 KO tumors was observed." (PMID 35965501, 2022). "Regulatory T cells (Tregs) have similar immune profiles in tertiary lymphoid structures of lung cancer and non-TLS areas, with tumor-infiltrating Tregs found to inhibit the proliferation and cytokine secretion of CD4 + conventional T cells." (PMID 36566320, 2022). "Extensive research has shown that intestinal microbes stimulate the expression of chemokines such as TNF- α, IL-6, IL-10, and IL-1β or activate cytotoxic lymphocytes, such as CD4+ and CD8+ T cells or NK and NKT cells, in both peripheral blood and tumor to limit tumor growth." (PMID 36232344, 2022). "In particular, bevacizumab may normalise the aberrant vascular–immune crosstalk by reorganising malformed tumour vessels to improve the infiltration of CD8+ T and CD4+ TH1 cells into the TME." (PMID 36230538, 2022). "The difference in the percentages of CD8+T and CD4+T cells between tumor and paratumor tissues also had no statistical significance." (PMID 36420264, 2022). "Our results indicate that the infiltration of only one type of immune cell, such as CD4+ or FOXP3+ cells, might be sufficient for a suitable tumour microenvironment to prevent recurrence." (PMID 36253752, 2022). "In tumor tissues, the higher the expression of CX3CL1, the higher the number of T cells, whether it is CD8+ T cells or CD4+ T cells." (PMID 35530333, 2022). "Moreover, strong negative correlations were observed between levels of FoxP3−Helios− T cells with CD4+TIM-3+ T cells and CD4+LAG-3+ T cells in tumor tissues (r = −0.825, p < 0.0001; r = −0.672, p = 0.0006, respectively) but not in PBMCs and NILs." (PMID 35455287, 2022).
tumor (continued). "Interestingly, knockdown of MYOSLID also increased the percentage of CD4+ and CD8+ T cells in subcutaneously transplanted tumours." (PMID 36139524, 2022). "Notably, CEP192 was highly correlated with multiple tumor-associated cytokine ligand–receptor axes, including IL11–IL11RA, IL6–IL6R, and IL13–IL13RA1, which could promote interactions between hepatic progenitor-like cells, PLVAP+ endothelial cells, tumor-associated macrophages, and CD4+ T cells." (PMID 36238304, 2022). "Moreover, tumor-specific antigens, transcription factor TOX, and CXCL13 are also expressed by T CD4+ lymphocytes carrying CD39+ and PD-1+." (PMID 37305016, 2022). "These phenotypes were further supported with additional immune markers including PD-1, PD-L1, granzyme B, FoxP3, CD20, CD4, CD3, CD45RO, TCF1, CD103, and CD95 to investigate the complexity of immunity in the tumor microenvironment of the lung cancer patients’ tissues." (PMID 36050391, 2022). "We also saw a correlation between tumor burden and TIGIT expression in CD4 and CD8 T cells." (PMID 34165864, 2022). "Similar to T-VEC, GEN0101 was predicted to induce the dense intratumoral infiltration of CD4+ and CD8+ T cells, which may have contributed to tumor cell death, according to previous clinical study." (PMID 34984539, 2022). "In addition, following PDT, the DCs highly express MHC-I and MHC-II molecules, bind with tumor antigens, form molecular complexes, present them to T cells, and start MHC-I restricted CTL reaction as well as MHC-II restricted CD4 + THL reaction." (PMID 36355531, 2022). "The activation and polarization of CD4+ T cells into Th1 phenotype is accompanied by a heightened ability to produce and secrete effector cytokines such as IFN-γ and TNF-α that have direct anti-tumor activities." (PMID 36605208, 2022). "Interestingly, only CD4+ MAIT cells demonstrated increased CD25 expression, while CD154 levels were comparable on all T‐cell populations in the circulation and the tumor microenvironment." (PMID 35028137, 2022). "Furthermore, a strong positive correlation was found between levels of FoxP3+Helios+ Tregs and CD4+CTLA-4+ T cells (r = 0.695, p = 0.0007) in tumor tissues." (PMID 35455287, 2022). "This study did not investigate the effects of TAS CD4+ T cells because CD8+ T cells are the main divers of tumor rejection in this model system." (PMID 35198900, 2022). "Anti-tumor immune responses of NDV-MIP3(a recombinant oncolytic Newcastle virus expressing MIP-3α) were partly reliant on CD8+ T cells and partially dependent on CD4+ T cells." (PMID 35488303, 2022). "However, CD3+, CD4+, and CD8+ T cell proportions were comparable in SCCCs versus ACCs, either in the total region or tumorous and stromal regions." (PMID 36032124, 2022). "In a mouse model bearing subcutaneous TC-1 lung tumor, this combined therapy resulted in tumor eradication in 60% of treated mice, which could be attributed to the enhanced function of CD8+ T cell, reduced ratio of Treg/CD4+ cell and the regulation to MDSCs." (PMID 35757741, 2022). "In addition, using the online server TIMER, we evaluated the relationship between the expression of PCMT1 and tumor immune infiltrating cell biomarkers, including B cells, CD8+ T cells, CD4+ T cells, macrophages, neutrophils, and dendritic cells." (PMID 35535040, 2022). "CD3+ (tumor, P = 0.0491; total, P = 0.0218), CD3+CD4+ (tumor, P = 0.0201; total, P = 0.0305), and CD20+ cells (tumor, P = 0.0425; stroma, P = 0.0214; total, P = 0.0176) and TLS (P = 0.0433) were more abundant in the TIME of MPR patients over that of the non-MPR patients." (PMID 36275670, 2022). "Likewise, CD4 T cells expressing PD-1 and CD39 at the tumor site were shown by us and others to be exhausted and tumor-Ag-specific." (PMID 35954341, 2022).